MYC (MYC proto-oncogene, bHLH transcription factor)
Diseases named in the same sentence as MYC in open-access papers (continued):
Sharing a sentence is not in itself a finding about the gene and the disease.
B-cell lymphoma (continued). "HGBL is comprised of two types, i.e., HGBL with MYC and Bcl-2 and/or Bcl-6 rearrangements (HGBL-DH or HGBL-TH) and HGBL-NOS, which replaced the category of B-cell lymphoma, unclassifiable, with features intermediate between DLBCL and BL (BCLU)." (PMID 35686130, 2022). "We found that c-MYC and BCL-2 are key targets of the MSI2/PRMT5 axis, which drives resistance to PRMT5 inhibition in B-cell lymphomas." (PMID 36167829, 2022). "The translocations of MYC and BCL2 and/or BCL6 in patients with high-grade B-cell lymphomas remained a significant independent predictor of a poorer PFS and OS, but the standard of care for these patients has not been established." (PMID 35153779, 2022). "Cytogenetic FISH testing for rearrangements of MYC and BCL2 and/or BCL6, helps to identify double-hit or triple-hit, high grade B-cell lymphoma with even poorer outcome and the need for more intensive treatment plans." (PMID 35626243, 2022). "We also assessed the response to M-100 in human B-cell lymphoma cell lines of the BL and DLBCL type characterized by MYC translocation or amplification, although the individual MYC mutation profile differed greatly in these cells." (PMID 36068335, 2022). "Chromosomal rearrangements commonly occur in B-cell lymphomas, mainly involving BCL2 gene at 18q21 chromosomal locus, BCL6 at 3q27 and MYC at 8q24." (PMID 33768318, 2021). "A practical algorithmic approach for the diagnosis of mature aggressive B-cell lymphoma proposes MYC-R detection first, followed by BCL2 and BCL6 gene analyses in MYC rearranged cases." (PMID 33768318, 2021). "We report here a case of high-grade B-cell lymphoma with MYC and BCL6 rearrangements relapsing as a high-grade plasmablastic neoplasm with MYC and BCL6 rearrangements after R-CHOP and R-EPOCH therapy." (PMID 35004320, 2021). "When MYC translocation occurs simultaneously with BCL2 and/or BCL6, the cases are classified as DH/TH high-grade B-cell lymphoma." (PMID 34207773, 2021). "The World Health Organization’s classification of large B-cell lymphomas now includes a new entity called “double hit high-grade B cell lymphoma” (HGBL), in which MYC rearrangement is combined with a BCL2 and/or BCL6 rearrangement." (PMID 35096627, 2021). "BL is an uncommon form of highly aggressive B-cell non-Hodgkin lymphoma, in whose pathogenesis several other oncogenes, such as TCF3, collaborate with MYC." (PMID 33801599, 2021). "Here we report the clinical, histological and immunohistochemical characterization of a canine subset of MYC and BCL2-negative, high-grade B-cell lymphomas sharing similarities with B-LL." (PMID 33816589, 2021). "Aggressive B-cell lymphomas gain MYC and BCL2 alterations through mechanisms other than gene translocations, and 18–44% of DLBCLs have been reported to express MYC and BCL2 concurrently." (PMID 33182440, 2020). "MYC rearrangements occur in 5–15% of diffuse large B-cell lymphomas (DLBCL), 20–35% of high-grade B-cell lymphoma, NOS (HGBL-NOS), and 90% of Burkitt lymphoma (BL)." (PMID 32260556, 2020). "PAFAH1B2, which is involved in ether lipid metabolism, may also be broadly dysregulated in many types of cancer and its over-expression at the transcriptional and at the protein levels in MYC-negative high-grade B-cell lymphomas is associated with good prognosis." (PMID 32373530, 2020). "An initial diagnosis of an aggressive mature B cell lymphoma should incorporate the assessment of cytological and immunohistochemical features, including the COO, and the percentage of MYC- and BCL2-expressing cells." (PMID 31388760, 2019).
B-cell lymphoma (continued). "Bioinformatics integration of all data sets revealed different MYC-binding patterns and transcriptional profiles in MYC-positive BL and DLBCL cell lines indicating different functional roles of MYC for gene regulation in aggressive B-cell lymphomas." (PMID 30953469, 2019). "Burkitt lymphoma (BL) is a highly aggressive B cell non-Hodgkin lymphoma (NHL) characterized by the translocation and deregulation of the MYC gene on chromosome 8 with the potential to involve multiple organ systems." (PMID 31115699, 2019). "Dual-targeting of MYC and EZH2 has been employed to disrupt MYC-EZH2 oncogenic axis in aggressive B cell lymphoma cells." (PMID 31752930, 2019). "There are two types of aggressive B-cell lymphoma, namely Burkitt lymphoma (BL) and a subgroup of diffuse large cell lymphoma (DLBCL), which both carry MYC translocations and overexpress MYC but both differ significantly in their clinical outcome." (PMID 30953469, 2019). "HGBL, with MYC and BCL2 and/or BCL6 and HGBL, NOS replaces the 2008 category of B-cell lymphoma, unclassifiable, with features intermediate between DLBCL and Burkitt lymphoma (BCLU)." (PMID 31484540, 2019). "In parallel with experiments on DH-My6 cells, four B-cell lymphoma cell lines with a GCB type, including two DLBCL cell lines (Su-DHL-5 and HT) and two MYC/BCL2 DHL cell lines (Su-DHL-10 and Nu-DHL-1), were also tested." (PMID 30323893, 2018). "Significant advancement in recent years has been made in better understanding MYC alterations of DLBCL and the updated WHO classification of high grade B-cell lymphoma." (PMID 29482573, 2018). "MYC activation can be found in nearly 50% of plasmablastic lymphomas (PBL), a rare, aggressive B cell lymphoma, usually occurring in patients with immunodeficiency or immunosuppression related to ageing, therapy, or the presence of EBV infection." (PMID 28375188, 2017). "To address these issues, we systematically studied the clinicopathologic features of 157 patients with MYC/BCL2 DHL including 108 with de novo disease and 49 patients with a history of low-grade B-cell lymphoma, mostly FL." (PMID 27203548, 2016). "In this retrospective study, we assess 157 patients with MYC/BCL2 DHL including 108 patients with de novo disease and 49 patients with a history of FL or rarely other types of low-grade B-cell lymphoma." (PMID 27203548, 2016). "Double hit lymphoma represents up to 14% of the patients with aggressive B-cell lymphoma and MYC/BCL2 DHL is most common, representing approximately 65% of all cases, followed by MYC/BCL2/BCL6 triple hit lymphoma, ~20%, and MYC/BCL6 DHL, ~15%." (PMID 27203548, 2016). "Detection of MYC rearrangement has become an aid in the diagnosis of BL and PBL and a prognostic marker in other aggressive B-cell lymphomas." (PMID 26416427, 2015). "The incidence and prognostic role of MYC and BCL2 rearrangements in mature B-cell lymphomas have been extensively studied, except the infrequent mantle cell lymphoma (MCL)." (PMID 26517511, 2015). "A recent study using an Eμ-c-Myc driven B-cell lymphoma mice model, demonstrated that ARTD8 is overexpressed in mouse B-cell lymphoma and can facilitate B-lymphoid oncogenesis and alterations in developmental progression driven by c-MYC." (PMID 26654227, 2015). "We analyzed 46 B-cell lymphoma (B-NHL) specimens with known karyotypes for translocations of IGH-, BCL2-, BCL6- and MYC-genes." (PMID 24733537, 2014). "In our case, image-guided core biopsy demonstrated a CD20-positive, MYC-rearranged B-cell lymphoma with a nearly 100% Ki-67 proliferation index and no BCL2 or BCL6 rearrangements." (PMID 41362384, 2025). "Three (4%) patients harbored MYC and BCL6 rearrangements, while none exhibited high-grade B-cell lymphoma with MYC and BCL2 and/or BCL6 rearrangements." (PMID 40715072, 2025). "Histopathologic analysis revealed a malignant B-cell lymphoma with a MYC gene rearrangement in the absence of BCL2 or BCL6 rearrangements, consistent with a high-grade lymphoma." (PMID 41362384, 2025).
B-cell lymphoma (continued). "Furthermore, cytogenetic profiling is crucial in identifying MYC, BCL2, and BCL6 rearrangements in high-grade B-cell lymphomas (HGBL-MYC/BCL2/BCL6), which define cases with aggressive clinical behavior and poor prognosis." (PMID 40150070, 2025). "Taking into account their variable morphology but homogeneous biological features and gene expression patterns, “double hit” cases with dual MYC and BCL2 rearrangements are designated diffuse large B-cell lymphoma/high-grade B-cell lymphoma with MYC and BCL2 rearrangements (DLBCL/HGBL-MYC/BCL2)." (PMID 38835969, 2024). "All four of these cases with variant MYC FISH results also had BCL2 rearrangements, raising the possibility of high-grade B-cell lymphoma with MYC and BCL2 rearrangements, without a definitive diagnosis." (PMID 38903717, 2024). "A biopsy confirmed high-grade mature B-cell-lymphoma with 11q aberration but lacking MYC/8q24 rearrangement." (PMID 38773265, 2024). "Large B-cell lymphomas with a MYC rearrangement, along with B-cell lymphoma 2 (BCL2) and/or B-cell lymphoma 6 (BCL6) rearrangements, are being classified as high-grade B-cell lymphomas (HGBLs) and are frequently referred to as double-hit (DHL) and triple-hit lymphomas (THL), respectively." (PMID 38397877, 2024). "MYC suppresses autophagy in B cell lymphomas by antagonizing the function of TFEB transcription factors, raising the possibility that PITPNC1 could control autophagy through MYC in LUAD and PDAC." (PMID 37210549, 2023). "Furthermore, the poor prognosis of B-cell lymphoma patients with exosomal BCL6 and MYC mRNA was observed at diagnosis." (PMID 37182123, 2023). "The c-MYC oncogene is activated in almost all human cancers and is most likely the critical driver in most if not all GC derived B-cell lymphoma." (PMID 37035206, 2023). "A biopsy of the right mammary gland tumor was performed, showing CD20 (+), CD21 (-), bcl-2 (+), CD10 (+), CD30(-), bcl-6 (+), MUM-1 (+), C-myc (70%+), CD19 (+), TDT (-), MPO (-), Ki-67 (+90%), MYC, and BLC2 rearrangements; a pathological diagnosis of high-grade, double-hit B-cell lymphoma was made." (PMID 36032118, 2022). "M-100 targets almost exclusively B-cell lymphoma cells with high levels of MYC whereas non-tumor cells are not affected." (PMID 36068335, 2022). "Interestingly, the latest subclassification of DLBCL contains a cluster of human B-cell lymphomas, driven by deregulated methyl transferases, such as EZH2 or MLL4, that often occur together with MYC and BCL-2 alterations." (PMID 36611833, 2022). "Intraocular manifestations of systemic DLBCL are rare and there are no data about intraocular manifestations of high-grade B-cell lymphoma with MYc and BCL6 rearrangements." (PMID 35334633, 2022). "To further study whether c-MYC plays a role in resistance to PRMT5 and MSI2 inhibition, we used the B-cell lymphoma cell line, P-4936 cells, that express c-MYC under the control of a tetracycline-inducible promoter." (PMID 36167829, 2022). "Approximately 30% of MYC + large B-cell lymphoma patients have a MYC rearrangement (single hit (SH) DLBCL), whereas in 70% MYC rearrangements are detected together with BCL2 and/or BCL6 rearrangements (double hit (DH) or triple hit (TH) high grade B-cell lymphomas)." (PMID 34476551, 2022). "The 2016 revised World Health Organization guidelines of lymphoid neoplasms classified large B-cell lymphoma with rearrangements of MYC and BCL2 or/and BCL6 in a distinct category to be designated high-grade B-cell lymphoma, also called double-hit lymphoma (DHL) or THL." (PMID 34113336, 2021). "In this model, the fusion cassette is not positioned at the endogenous Ig locus, MYC expression is still restricted to B cells and these mice form B-cell lymphomas." (PMID 34585724, 2021).
B-cell lymphoma (continued). "Molecular analysis of the disease developed in this model reveals an upregulation of the c-Myc oncogene via post-transcriptional and translational mechanisms underscoring the impact of non-genomic MYC activation in B-cell lymphomas." (PMID 33912162, 2021). "The regulation of MYC by hnRNP K occurs at the post-transcriptional and translational level, indicating that hnRNP K over-expression represents a key non-genomic mechanism of MYC regulation in B-cell lymphomas." (PMID 33912162, 2021). "Between five and ten percent of DLBCL have concurrent rearrangements of MYC, BCL2, and/or BCL6 and are now recognized as a distinct entity in the 2016 WHO classification of lymphoid neoplasms as ‘high-grade B-cell lymphoma with MYC, BCL2, and/or BCL6 rearrangements (DHL/THL)’." (PMID 34830747, 2021). "MYC overexpression is also inversely correlated with tumor necrosis factor (TNF) super family members lymphotoxin-α(TNFSF1), lymphotoxin-β and TNF-α, that play a role in T cell recognition, cell-to-cell communication and adhesion in B cell lymphoma cell lines." (PMID 33092116, 2020). "We show that Co-expression of c-MYC and BCL2 in germinal center (GC) B cells or pan-B cells could induce B cell lymphoma." (PMID 32695674, 2020). "Furthermore, MYC repressed CD80 in both an EBV transformed cell line and a transgenic B cell lymphoma mouse model." (PMID 33092116, 2020). "We observed that Co-expression of c-MYC and BCL2 in germinal center (GC) B cells, or pan-B cells could induce B cell lymphomas." (PMID 32695674, 2020). "Overall, our data indicated that c-MYC and BCL2 Co-expression in GC B cells could induce B cell lymphoma." (PMID 32695674, 2020). "In summary, these results illustrate that c-MYC and BCL2 Co-expression in pan-B cells could also induce B cell lymphoma." (PMID 32695674, 2020). "We observed that Co-expression of c-MYC and BCL2 in germinal center B cells, or pan-B cells could both induce B cell lymphoma." (PMID 32695674, 2020). "The debate about research into aggressive mature B-cell lymphomas with MYC, BCL2 and/or BLC6 aberrations, defined as high-grade B-cell lymphoma with double or triple hit (HGBL-DH/TH), deserves a special section as their detection constitutes a principal goal according to the last WHO classification." (PMID 31940809, 2020). "Of note, with these studies, it became clear that CD79 and MYD88 mutations were mutually exclusive with other known recurrent alterations occurring in DLBCLs, such as translocations of MYC and BCL2 and/or BCL6, as observed in the new WHO category of high-grade B-cell lymphomas." (PMID 33050534, 2020). "We found that Co-expression of c-MYC and BCL2 in germinal center B cells could induce B cell lymphoma." (PMID 32695674, 2020). "Moreover, in B-cell lymphomas a link between MYC and BCL-2 expression has been described, because overexpression of MYC in tumor cells is often found together with rearrangements in the BCL-2 family to support tumor growth and suppress apoptosis." (PMID 29371588, 2018). "But the recognition of DLBCL with MYC and/or BCL2 overexpression could be used to expand the spectrum of aggressive B-cell lymphomas and effective stratify patients." (PMID 29674626, 2018). "Rearrangements of MYC, BCL2, and/or BCL6 can be demonstrated using conventional cytogenetic techniques (karyotype) and/or FISH; this is a requirement for the diagnosis of cases of high-grade B cell lymphoma with DH/TH (Grade 2A)." (PMID 30190794, 2018). "At present time, the clinical significance of somatic hypermutations of c-MYC in BL and other B-cell lymphomas is not established." (PMID 28379189, 2017). "In contrast, the study by Aukema and colleagues showed that the MYC partner (IG versus non-IG) had no prognostic significance in MYC rearrangement positive B-cell lymphoma (excluding Burkitt lymphoma)." (PMID 27203548, 2016).
B-cell lymphoma (continued). "Interestingly, a link between the miR-29 family by MYC has been recently reported, as repression of miR-29 by MYC through a corepressor complex with HDAC3 and EZH2 is observed in aggressive B-cell lymphomas." (PMID 26453442, 2015). "Preclinical and early clinical studies demonstrated that ABT-199 inhibits the growth of aggressive c-MYC-driven mouse B-cell lymphomas and human BCL2-dependent B-cell lymphoma tumors in vivo without causing thrombocytopenia." (PMID 26654227, 2015). "These cases are MYC-negative, high-grade B-cell lymphomas sharing a recurrent pattern of 11q aberration and similarities with but not being BL." (PMID 26416427, 2015). "Our results extend the current knowledge on aggressive B-cell lymphomas presenting with MYC expression but lacking a conventional translocation." (PMID 26453442, 2015). "Steady state mRNA levels of MYC in a non-BL murine B cell lymphoma line (BAL17) that over expresses MYC at levels similar to the BL cells and HeLa cells showed no significant sensitivity to JQ1." (PMID 24466310, 2014). "Salaverria and Siebert suggest that adult aggressive B-cell lymphomas lacking typical BL morphology and phenotype can be classified thereafter into four different genetic subcategories according to their MYC status as follows." (PMID 22548066, 2012). "The diagnosis of this type of unclassifiable B-cell lymphoma category should not be made in cases of morphologically typical DLBCL that have a MYC rearrangement or in otherwise typical BL in which a MYC rearrangement cannot be demonstrated." (PMID 22190944, 2012). "Notably, the classification of high-grade B-cell lymphoma characterised by dual rearrangements involving MYC and either BCL2 or BCL6 has been redefined as DLBCL with high-grade B-cell lymphoma with MYC/BCL2 (DLBCL/HGBL-MYC/BCL2)." (PMID 40572636, 2025). "Based on this limited available data, FL-BCL2-R/MYC-R should not be included within the category of high-grade B-cell lymphoma since most of the cases have a good outcome At this point, it is not recommended to perform MYC FISH analysis for FL routine diagnosis." (PMID 40616614, 2025). "In cases where high-grade cytology, high MYC (>40%) and BCL2 (>50%) expression, and the GCB phenotype are present, FISH analysis is recommended to assess for MYC and BCL2 rearrangements, which define high-grade B-cell lymphoma with MYC/BCL2 rearrangements, according to the 2022 WHO classification." (PMID 40881873, 2025). "However, unlike in BL, MYC rearrangements in other aggressive B-cell lymphomas do not usually involve the IGH gene and are more frequently the result of rearrangements with either IG k, IG λ, or non-IG genes." (PMID 41154426, 2025). "Additionally, a subset of B-cell lymphomas that histologically resemble BL do not have the MYC rearrangement but possess 11q aberrations." (PMID 40428800, 2025). "Interestingly, although TFEB is an eIF5AHyp translation target in normal B cells (see Section 2.3.1), TFEB is transcriptionally suppressed in MYC overexpressing B cells, and is thus not detected as a target of eIF5AHyp in B-cell lymphoma." (PMID 39125743, 2024). "However, in contrast to non-lymphoid tumors where translocations are rare, MYC is frequently translocated and deregulated in B cell lymphomas and in virtually all cases of Burkitt lymphoma." (PMID 39766110, 2024). "In addition to histologic classification, further testing for rearrangements of MYC, BCL-2, and BCL-6 is important, as these genetic alterations are associated with poor prognosis, particularly the “double-hit” MYC/BCL-2, currently classified by the WHO-HAEM5 as high-grade B-cell lymphoma." (PMID 39749087, 2024). "However, the 2022 World Health Organization (WHO) and International Consensus Classification (ICC) recommendations re-categorized MYC/BCL6 as “DLBCL, not otherwise specified” and MYC/BCL2 and MYC/BLC2/BCL6 as “DLBCL/high-grade B-cell lymphoma-MYC/BCL2”." (PMID 39696503, 2024).